ADGRB3 (adhesion G protein-coupled receptor B3)
Description:
Receptor that plays a role in the regulation of synaptogenesis and dendritic spine formation at least partly via interaction with ELMO1 and RAC1 activity (By similarity). Promotes myoblast fusion through ELMO/DOCK1.
Synonyms: BAI3; KIAA0550
Tractability: Small molecule: a structure with a bound ligand is known. Antibody: UniProt places it where antibodies can reach, with high confidence; its Gene Ontology location is reachable by antibodies, with high confidence; UniProt predicts a signal peptide or a membrane-spanning region. PROTAC: its protein half-life has been measured.
Gene: Protein-coding gene on chromosome 6 (68,635,282 to 69,390,571, forward strand). Ensembl gene ENSG00000135298.
Subcellular location: Cell membrane
Gene Ontology:
Molecular function: protein binding; G protein-coupled receptor activity; GTPase activator activity; transmembrane signaling receptor activity
Biological process: myoblast fusion; G protein-coupled receptor signaling pathway; neuron remodeling; regulation of dendrite morphogenesis; cell differentiation; cell surface receptor signaling pathway; negative regulation of angiogenesis; regulation of synapse maturation; regulation of synapse pruning
Cellular component: plasma membrane; membrane; postsynapse; synaptic cleft; cerebellar climbing fiber to Purkinje cell synapse; postsynaptic density membrane
Genetic constraint (gnomAD): Loss-of-function variants: 28 observed, 156.28 expected, observed/expected ratio (o/e) 0.18, 90% interval 0.13 to 0.25. The upper end of that interval is the gene's LOEUF score, 0.25, which puts it in group 1 of 6, group 1 being the genes least tolerant of losing a copy. Missense variants: 1,442 observed, 1,717.4 expected, observed/expected ratio (o/e) 0.84, 90% interval 0.8 to 0.88. Synonymous variants: 633 observed, 614.94 expected, observed/expected ratio (o/e) 1.03, 90% interval 0.96 to 1.1.
Homologues: Orthologues: chimpanzee ADGRB3 (99% identical), macaque ADGRB3 (99% identical), rabbit ADGRB3 (99% identical), dog ADGRB3 (99% identical), mouse Adgrb3 (98% identical), pig ADGRB3 (98% identical), rat Adgrb3 (98% identical), guinea pig ADGRB3 (96% identical), tropical clawed frog adgrb3 (89% identical), zebrafish adgrb3 (63% identical). Paralogues in human: ADGRB2 (49% identical), ADGRB1 (48% identical), ADGRL1 (13% identical), ADGRL2 (13% identical), ADGRA3 (12% identical), ADGRL3 (12% identical), ADGRA2 (11% identical), ADGRF5 (11% identical), ADGRD1 (11% identical), ADGRG4 (11% identical), ADGRF1 (10% identical), ADGRG6 (10% identical), and 30 more.
Diseases named in the same sentence as ADGRB3 in open-access papers:
ADGRB3 is named in the same sentence as 44 diseases in open-access papers, as found by Europe PMC text mining. Sharing a sentence is not in itself a finding about the gene and the disease. The quoted sentences say what the papers report.
glioma (3 papers, 2013 to 2024). A benign or malignant brain and spinal cord tumor that arises from glial cells (astrocytes, oligodendrocytes, ependymal cells). "Protective genetic changes in glioma include increased expression of ADGRB3/1, IL12B, DYRKA1, VEGFC, LRRC4, and BMP4." (PMID 39022728, 2024).
Alzheimer disease (1 paper, 2024). A progressive, neurodegenerative disease characterized by loss of function and death of nerve cells in several areas of the brain leading to loss of cognitive function such as memory and language. "In both cases, the specific mechanisms by which TAS2R41 and TAS2R60 influence the expression or function of EPHB6 and ADGRB3 in the context of Alzheimer's disease remain to be fully elucidated." (PMID 39284855, 2024).
Cerebellar atrophy (1 paper, 2021). Cerebellar atrophy is defined as a cerebellum with initially normal structures, in a posterior fossa with normal size, which displays enlarged fissures (interfolial spaces) in comparison to the foliae secondary to loss of tissue. "Similarly, ADGRB3, also does not belong to the pathway that was sequenced in the US cohort, but it has been associated with intellectual disability and cerebellar atrophy." (PMID 33974636, 2021).
gastric adenocarcinoma (1 paper, 2024). "Two stage-salient genes, namely CNTN1 and BAI3 (ADGRB3) were documented as putative tumor suppressor genes involved in gastric adenocarcinoma, providing specific support for our findings." (PMID 39484215, 2024).
Infertility (1 paper, 2021). "Of interest, some candidates related to sperm and infertility were identified, containing MORC1, TDRD9, ZFYVE21, ADGRB3, SPAG17, CKB, and WDR3, which may have effects on sperm motility and fertilization." (PMID 33477586, 2021).
nasal polyps (1 paper, 2024). "POSTN+ fibroblasts showed a gradually increasing trend among the CM, UT, and NP groups, indicating that the two cell types (POSTN+ fibroblasts and ADGRB3+ fibroblasts) may play a mutual role in the occurrence and development of nasal polyps." (PMID 38280891, 2024). "ADGRB3+ fibroblast levels were highest in the tissues of the control group, followed by the UT and NP groups, suggesting that this cell subgroup type may be a protective factor against the occurrence and development of nasal polyps, similar to tumor suppressor genes." (PMID 38280891, 2024).
venous thromboembolism (1 paper, 2017). Occlusion of the lumen of a vein by a thrombus that has migrated from a distal site via the blood stream. "A previous GWAS identified SNPs at the ADGRB3 locus as associated with early-onset venous thromboembolism." (PMID 28056976, 2017).
tumor (10 papers, 2006 to 2024). "ADGRB3 is an angiogenesis inhibitor, which has been found to be the most significantly mutated gene in 13% of lung squamous tumours, with mutations resulting in decreased activity of the receptor, increasing blood flow to the tumour." (PMID 34282836, 2021). "In the EMMAX corrected dataset rs6698333, an intron variant of Kruppel-like factor 17 (KLF17) and two SNPs (rs1889877, rs3798999) in the intron of adhesion G protein-coupled receptor B3 (ADGRB3) were significantly (< 10-5) associated with ERG fusion status of the index tumor." (PMID 32341752, 2020). "Furthermore, it was discovered that in many lung cancers, the translation of ADGRB3 is decreased, resulting in reduced tumour suppressive effects provided by the receptor." (PMID 34282836, 2021).
infection (4 papers, 2017 to 2024). The state of being infected such as from the introduction of a foreign agent such as serum, vaccine, antigenic substance or organism. "In Calu-3 cells, the relative mRNA expression upon infection with infectious SARS-CoV-2 exhibited a pronounced increase in the cases of ADGRD1/GPR133 and ADGRG7/GPR128, a small increase in the case of ADGRB3/BAI3 and a negligible change in that of ADGRV1/GPR98 mRNA levels after 24 and 48 h." (PMID 38786015, 2024). "In Caco-2 cells, no increase in mRNA expression of ADGRB3/BAI3, ADGRG7/GPR128 and ADGRV1/GPR98 was detected even 48 h after infection, thus confirming our results after 12 h post infection." (PMID 38786015, 2024).
ADGRB3 also shares sentences with these, for which no sentence is quoted: cancer (6 papers); schizophrenia (5); bipolar disorder (4); ovarian carcinoma (3); psychiatric disorder (3); small cell lung carcinoma (3); Anxiety (2); glioblastoma (2); lung carcinoma (2); melanoma (2); neurological diseases (2); Ataxia (1); autism (1); brain ischemia (1); breast carcinoma (1); Cognitive impairment (1); developmental delay (1); emotional instability (1); esophageal carcinoma (1); Hearing impairment (1); hearing loss (1); high-grade gliomas (1); hypertrophic cardiomyopathy (1); injury (1); Intellectual disability (1); ischemia (1); ischemic stroke (1); large-cell neuroendocrine lung carcinoma (1); lung adenocarcinoma (1); lung squamous cell carcinoma (1).
A further 5 diseases each share a sentence with ADGRB3 in 1 paper.